CLCN4 (Cl-/H+ antiporter 4)
Description:
Strongly outwardly rectifying, electrogenic H(+)/Cl(-)exchanger which mediates the exchange of chloride ions against protons. The CLC channel family contains both chloride channels and proton-coupled anion transporters that exchange chloride or another anion for protons. The presence of conserved gating glutamate residues is typical for family members that function as antiporters.
Synonyms: ClC-4; CLC4; ClC-4A; MRX15; MRX49; MRXSRC
Tractability: Small molecule: it belongs to a druggable protein family. Antibody: UniProt predicts a signal peptide or a membrane-spanning region; its Gene Ontology location is reachable by antibodies, with medium confidence. PROTAC: ubiquitination databases record sites on it; its protein half-life has been measured.
Gene: Protein-coding gene on chromosome X (10,156,943 to 10,237,660, forward strand). Ensembl gene ENSG00000073464.
Subcellular location: Early endosome membrane; Late endosome membrane; Endoplasmic reticulum membrane; Lysosome membrane; Recycling endosome membrane
Subcellular location (Human Protein Atlas): Vesicles
Pathways (Reactome):
Transport of small molecules: Stimuli-sensing channels
Gene Ontology:
Molecular function: antiporter activity; chloride channel activity; protein binding; voltage-gated chloride channel activity; chloride transmembrane transporter activity
Biological process: chloride transport; monoatomic ion transmembrane transport; chloride transmembrane transport; transmembrane transport
Cellular component: endoplasmic reticulum membrane; endosome membrane; late endosome membrane; lysosomal membrane; recycling endosome; recycling endosome membrane; early endosome membrane; Golgi apparatus; plasma membrane; synaptic vesicle; membrane
Gene-disease validity (ClinGen):
ClinGen rates the evidence that CLCN4 causes each of these diseases.
non-syndromic X-linked intellectual disability (X-linked): Definitive. Nonspecific X-linked intellectual deficiencies (MRX) belong to the family of sex-linked intellectual deficiencies (XLMR).
Homologues: Orthologues: chimpanzee CLCN4 (100% identical), macaque CLCN4 (99% identical), dog CLCN4 (99% identical), rat Clcn4 (99% identical), pig CLCN4 (98% identical), guinea pig CLCN4 (98% identical), mouse Clcn4 (97% identical), tropical clawed frog clcn4 (95% identical), zebrafish clcn4 (89% identical), Drosophila melanogaster ClC-c (61% identical), Caenorhabditis elegans clh-5 (54% identical). Paralogues in human: CLCN5 (77% identical), CLCN3 (77% identical), CLCN7 (29% identical), CLCN6 (28% identical), CLCN2 (27% identical), CLCN1 (25% identical), CLCNKB (22% identical), CLCNKA (21% identical).